PDGFRA (platelet derived growth factor receptor alpha)
Diseases named in the same sentence as PDGFRA in open-access papers (continued):
Sharing a sentence is not in itself a finding about the gene and the disease.
tumor (continued). "In addition, a strong upregulation of PDGFRα and PDGFRβ was detected in hSCC11 PD/S cells, indicating that tumor cells from human advanced SCCs induce PDGFR signaling." (PMID 30874597, 2019). "The ratio of PDGFRA to PDGFRB expression in primary tumors may be predictive of tumor response to TMZ." (PMID 31336733, 2019). "Analysis of hematoxylin and eosin-stain images showed that hTERT + PDGFRα + cMSC treatment did not cause structural change or tumour formation." (PMID 31332256, 2019). "Notably, PDGFRA expression on the cell surface is restricted to the stromal compartment in skin and tumour cells and the molecule is reportedly expressed by up to 90% of stromal fibroblasts in solid tumours." (PMID 31216299, 2019). "Lenvatinib also inhibits other RTKs including fibroblast growth factor (FGF) receptors FGFR1, 2, 3, and 4; the platelet-derived growth factor receptor alpha (PDGFRα); KIT; and RET that have been implicated in the pathogenic angiogenesis, tumor growth, and cancer progression." (PMID 31683894, 2019). "In addition, PDGFRα was, to some extent, expressed in the tumor epithelial-cells of 18% of the patients (20% of SCCs and 16% of ADCs) in the Norwegian cohort." (PMID 31308421, 2019). "Since transplantation of PDGFRα + cMSCs in vivo could result in unanticipated homing to other organs and possible tumour formation, we performed a full necropsy on each animal examining the heart, lung, spleen, kidney and liver." (PMID 31332256, 2019). "Together, these bioinformatics and experimental findings demonstrate that the NTRK fusion gene induced an enhanced overexpression and activation of other RTKs, suggesting a forward feedback loop within PI3K-AKT signaling, resulting in a more aggressive tumor than PDGFRA-driven HGG." (PMID 31420543, 2019). "PDGFRA expression in primary tumors may then be used to predict whether a tumor will be responsive to conventional TMZ treatment, or if a combinational therapy with Axitinib may be more effective." (PMID 31336733, 2019). "Interestingly, in the case of specific PDGFRα-mutant GISTs, preliminary results indicate that even telocytes can be a source cell population of this tumor." (PMID 30781716, 2019). "PDGFRα expression has been described both in stroma and in tumour cells." (PMID 29380207, 2018). "In our cohort, patients who developed CNS metastases had primary tumours with high expression of tumour cell PDGFRα in 67%, PDGF-CC in 50% and concomitant high ligand/receptor expression in 33% of cases, indicating an active role of the PDGF pathway in these tumours." (PMID 29380207, 2018). "Interestingly, we report for the first time a significant up-regulation of tumour cell PDGFRα expression in lymph node metastasis and asynchronous recurrences, as a sign of its role in tumour progression." (PMID 29380207, 2018). "Gain-of-function mutations in the growth factor receptor genes for KIT (CD117) and platelet-derived growth factor α (PDGFRA) drive tumor development in 85–90% of GISTs to promote constitutive activation of growth factor signaling pathways that cause uncontrolled cell proliferation." (PMID 30450193, 2018). "The cell-by-cell analysis and mixture modeling suggests that this ensemble average does not capture the subpopulations having high-PDGFR plasma membrane localization: 66 and 16% of mouse tumor EC-like cell membrane had ~23,400 PDGFRα and ~19,800 PDGFRβ, respectively." (PMID 30050899, 2018). "Moreover, the requirement for PDGFRα activity for the observed heightened VB sensitivity was best exemplified when DOX was withdrawn upon tumor detection and treated with VB, resulting in a shorter median survival (46 days)." (PMID 30082792, 2018). "The occurrence of the D842V mutation among the host oncogenic alterations that compensate for KSHV-loss, and the fact that it can override Imatinib inhibition of the KSHV-ve tumor growth, strongly supports the oncogenic driver role of PDGFRA signaling in these tumors." (PMID 29985958, 2018).
tumor (continued). "This pattern was repeated for PDGFRA, for which we observed a thin rim of cytoplasmic/membranous staining in the majority of tumour cells within Group 2 tumours, while only neurons were stained in Group 1 tumours." (PMID 29058119, 2018). "IHC for PDGFRA showed strong membrane staining of tumor cells." (PMID 30546832, 2018). "In the H3/IDH1 mutant tumor HGG5, a PDGFRA Y288C missense mutation was acquired at recurrence." (PMID 29084603, 2017). "TAS-115 monotherapy may benefit SS patients whose tumours are dependent upon either c-MET or PDGFRα signalling by functioning as a multiple tyrosine kinase inhibitor to suppress c-MET as well as PDGFRα pathways." (PMID 28511645, 2017). "Furthermore, an elevated level of p-AKT was observed in tumor tissues derived from PDGFRα-overexpressing Tsc2−/− or Tsc1−/− MEFs as compared to the control tissues." (PMID 28903387, 2017). "PDGFRα is known to play a major role in tumor angiogenesis by stimulation of cell growth." (PMID 28484518, 2017). "Differently, PDGFC is less expressed in microvascular proliferation in comparison to all other GBM regions aside from hyperplastic blood vessel and leading edge, and similarly to PDGFA and PDGFRA, it bears a preferential expression in cellular tumour bulk over leading edge." (PMID 29127351, 2017). "Among 95 patients, 62 patients (65.3%) showed positive for PDGFRα on tumor sites." (PMID 28465473, 2017). "We demonstrate here that CXCR4 signaling, which increases PDGFRα activity, could enhance tumor invasion ability." (PMID 28415580, 2017). "However, the results of direct sequencing revealed that there was no mutation in exons 9, 11, and 13 of the KIT gene or in exon 18 of the PDGFRA gene in the tumor." (PMID 28288693, 2017). "Moreover, overexpression of PDGFRα accelerated cell proliferation and tumor growth of Tsc1- or Tsc2-null MEFs." (PMID 28903387, 2017). "These tumor-associated myofibroblasts express ACTA2 and PDGFRα/β." (PMID 28806761, 2017). "Notably, we observed that the inhibition of tumor EMT by NT21MP correlates with the decreased expression of PDGFRα in the NT21MP-treated tumors compared with paclitaxel and the negative control." (PMID 28415580, 2017). "However, when conditionally deleted from the aRMS GEMM, PDGFRA-null mice exhibit an earlier onset and increase in tumor progression compared to those with intact PDGFRA." (PMID 28883017, 2017). "PDGFRα expression in tumor and matching non-tumor sites was compared." (PMID 28465473, 2017). "We conceived a double approach to answer this question, based on a) permanent intracellular fluorescence labelling of cultured CAFs by the fluorochrome 5-chloromethylfluorescein diacetat (CMFDA); and b) detection of human CAFs in tumor tissue by a human-specific anti-PDGFRα antibody." (PMID 28440285, 2017). "Regarded by many as reactive tumours of nonneoplastic origin until 2008, the neoplastic nature of IFPs became evident after the detection of activating PDGFRA mutations." (PMID 27781129, 2016). "We initially suspected the tumor to be a PDGFRα-positive GIST." (PMID 27842558, 2016). "Bertotti et al35 recently carried out exome sequence and copy number analyses of both patient‐derived xenografts and patient tumours, to investigate the effects of mutations in ERBB2, EGFR, FGFR1, PDGFRA and MAP2K1 in relation to resistance to anti‐EGFR therapies." (PMID 26690310, 2016). "The tumor cells in our case were partly epithelioid and immunohistochemically PDGFRα-positive." (PMID 27842558, 2016). "However, females prevail (14:5) also among the 19 ascertained PDGFRA-mutants, compensating the corresponding 10:4 female-to-male tumor distribution (coherently, Fisher exact test, one-tailed, proved not significant: p = 0.60)." (PMID 27437068, 2016).
tumor (continued). "Our study indicated that Nrf2 expression in HCC could not only increase PDGFA generation but also upregulate PDGFRα expression, leading to autocrine signaling in tumor cells." (PMID 27588483, 2016). "Moreover, among A1 patients with a tumor size >5 cm, those carrying a KIT or PDGFRA mutation (n = 11) had a worse prognosis than the WT (n = 3), the 2-year RFS rates being 58 and 100 % respectively." (PMID 26867653, 2016). "PDGFRα was expressed in all four RT cases with cytoplasmic staining in tumor cells." (PMID 27783942, 2016). "Still, the gene expression signature between H3.1 and H3.3 subgroups may not be due to the H3 mutations themselves but rather the accompanying alterations (PDGFRA vs. ACVR1) or differential modification of the microenvironment by tumour cells." (PMID 26399631, 2015). "Importantly, deactivation of PDGFR signaling in models with an amplified PDGFRA gene appeared to be involved in the induction of tumor regressions when regorafenib is given in combination with DNA damaging agents." (PMID 26599335, 2015). "In this study, we analyzed genotypes of VEGF-A, KDR, Flt4, PDGFRα, HIF-1α and ERCC1 in TETs, aiming to verify whether they correlate with increased tumor risk and/or with the outcome of these patients." (PMID 26254278, 2015). "Even in lesions with double mutations that show extreme imatinib resistance, imatinib may weakly inhibit the downstream signaling of KIT or PDGFRA and slows tumor progression." (PMID 24587795, 2014). "Targeting PDGFRα in the stromal compartment, particularly in the lung, may have therapeutic potential for inhibition of tumor growth." (PMID 25149088, 2014). "Furthermore, PDGFRα down-regulation by the Shh-I LDE225 in combination with vemurafenib enhances tumor growth inhibition in vitro and in vivo and decreases ERK and AKT activation in both sensitive and resistant cell lines." (PMID 24732172, 2014). "Further examination of its mechanism revealed that induction of EMT upon PDGFRα upregulation accounted for the enhanced tumor cells invasion, and thus compromised prognosis of HCC patients, as suggested by a recent study that EMT is involved in HCC recurrence after surgery." (PMID 25333264, 2014). "The tumor growth curve (the estimated tumor size calculated from the tumor dimension versus time) with imatinib was almost the same as with vehicle, which indicates in vivo resistance of BaF3-T674I PDGFRα cells to imatinib." (PMID 24472312, 2014). "Furthermore, VEGFR1 and -2 score and intensity as well as PDGFRα and -β score, intensity and vessel staining revealed higher mean expression in tumor tissues from patients with clinical parameters of poor prognosis." (PMID 24086736, 2013). "By contrast, MGMT methylation is common in tumours amplified for PDGFRA alone." (PMID 23990986, 2013). "Survival analysis indicated that mitotic count and Ki-67 protein expression levels were significant predictors of disease-specific survival; however, tumor size, primary location, c-kit and PDGFRA gene mutations were not." (PMID 23420829, 2013). "In addition, the receptor appeared to be activated in the xenograft based on intense positive staining with antibody against phospho-PDGFRA that was specific for the tumor cells." (PMID 23527265, 2013). "Strikingly, the same interplay between H3K4me3 and H3K27me3 occurs for master genes involved in the EMT process, such as PDGFRα, which is essential for Twist1 to promote tumor metastasis via invadopodia, and the splicing regulator ESRP1, which is repressed by Snail1 to promote EMT." (PMID 24367927, 2013). "Summary of immunohistochemical findings of microscopic tumor foci for β-catenin and PDGFRα." (PMID 22761897, 2012).
tumor (continued). "54.5% of all tumor foci in the WT mice showed cytoplasmic PDGFRα expression." (PMID 22761897, 2012). "KIT and PDGFRα genes code for their respective tyrosine kinase receptors, and known mutations result in constitutive activation driving the proliferation and survival of GIST tumor cells." (PMID 22429770, 2012). "In the group of 89 patients, whose initial tumor mutational status was evaluated, 58.4% of GISTs had an exon 11 KIT mutation, 16.9% had an exon 9 KIT mutation, 13.5% had PDGFRA gene mutation (11 of 12 cases had D842V mutation) and in 11.2% of tumors we have not detected any mutations (wild-type)." (PMID 22439647, 2012). "Disrupting the homeostatic equilibrium between miR-34a and PDGFRA potentially gives rise to a cancer-promoting, feed-forward loop, one that could ultimately lead to both cell proliferation and tumor formation." (PMID 22479456, 2012). "However, recent evidence suggests that expression of both PDGFRα and β, either in the tumor tissue or stroma, is correlated with invasive breast cancers and tumor progression." (PMID 22070644, 2011). "The distribution of PDGFRA mutant tumours between the low- and high-risk categories was significantly different from that of KIT mutant or wild-type tumours when using the AFIP classification (P=0.005, Kruskal–Wallis test), but not when using the NIH classification (P=0.452, Kruskal–Wallis test)." (PMID 20588273, 2010). "Approximately 85–90% of GISTs harbour activating mutations for the stem cell factor (SCF) receptor CD117 (c-Kit) or the alpha-type platelet-derived growth factor receptor (PDGFRα), which makes this tumour responsive to the tyrosine kinase inhibitor imatinib mesylate." (PMID 20859288, 2010). "Tumors with PDGFRA mutations showed the same overall pattern of alterations seen in those with KIT mutations, even if genomic complexity was much lower in the former (median of 2 vs. 5.5 alterations per tumor, respectively, P = 0.050, Mann-Whitney U test)." (PMID 20470368, 2010). "PDGFRA may regulate tumor angiogenesis by PDGFRA-p70S6K pathway which is related to the function of fibroblast growth factor (FGF) and expression of VEGF and hepatocytes growth factor (HGF)." (PMID 19948069, 2009). "VEGF and PDGFRA promote the tumor angiogenesis in inflammation and hypoxia conditions." (PMID 19948069, 2009). "However, a recent survey of patient archival biopsies showed that 93% of GBMs had detectable levels of PDGFRα and 37% had detectable PDGFRβ on tumor cells, while 93% and 100% had detectable levels in blood vessels, respectively." (PMID 19352490, 2009). "Tyrosine kinase inhibitors (TKIs; e.g., imatinib, sunitinib, regorafenib, ripretinib) were hypothesized to block the constitutive activation of KIT- and PDGFRA-mediated pathways, and have indeed demonstrated anti-tumor activity in clinical trials of patients with advanced GIST." (PMID 41264161, 2026). "The reason for this is unclear, but we speculate that Endocan may act together with PDGF-BB to maintain a high level of PDGFRa activation in the same tumor region, while other PDGFR ligands are expressed in the different GBM areas and may therefore affect other populations of GBM cells." (PMID 39773984, 2025). "Notably, PDGFRA expression was significantly higher in pontine DMGs compared to thalamic or spinal samples, indicating spatial specificity and potential correlation with tumor aggressiveness." (PMID 41036308, 2025). "PDGFRA-expressing cells are recognized fibroblast markers and mesenchymal progenitors, suggesting that methylation changes in its adjacent tissues may relate to tumor microenvironment formation and progression." (PMID 41184502, 2025). "Moreover, the proposed triad of gastric localization, primary tumor size greater than 10 cm, and low SUVmax may have a clinical utility in identifying PDGFRA-mutant GISTs, for better tailoring both molecular assessment and clinical decision-making." (PMID 39853981, 2025).
tumor (continued). "Tumours lacking variants in KIT or PDGFRA were traditionally called ‘wild-type’ (WT)." (PMID 38840030, 2025). "Together, these data support an integrated approach in which tumor size and Ki-67—interpreted alongside CD117, DOG1, and CD34, and complemented by molecular testing (KIT, PDGFRA, MMR status)—may contribute to diagnostic assessment and hypothesis generation for future risk stratification." (PMID 41465833, 2025). "However, in UCEC, dysregulation of COL1A1, ITGB1, THY1, and PDGFRA may compromise immune function, enabling tumor progression." (PMID 40817072, 2025). "Moreover, tumor development is reduced by inhibiting the PDGFRα-mediated signaling in CAFs." (PMID 39403603, 2024). "Thus, the G5/PDGFRA subgroup contains tumors with an amplification of PDGFRA with or without neighboring KIT and KDR RTK genes from the 4q12 chromosomal locus, and more rarely, a tumor with PDGFRA activating mutations without amplification." (PMID 38254850, 2024). "Thus, the decreased expression of PDGFRα in KO may contribute to the suppression of tumor formation and proliferation in KO." (PMID 39394459, 2024). "Therefore, PDGFRA plays an important role in tumor progression." (PMID 37454137, 2023). "To our knowledge, these lesions have so far been described in the gastrointestinal tract, but as we are speaking of a neoplasm originating from stromal cells, there is no clear reason why the causative PDGFRA mutation should occur in cells of the gastrointestinal stroma only." (PMID 37184764, 2023). "Notably, a total of 10 previously reported single-nucleotide polymorphisms (SNPs) were found in this tumor in genes including MLH1 (rs769364808), FGFR3 (rs769364808), two variants (rs1873778 and rs2228230) in PDGFRA, KIT (rs55986963), APC (rs41115), and RET (rs1800861)." (PMID 37273678, 2023). "To further confirm whether the mutations of PDGFRA and KIT could promote angiogenesis, we compared the Micro-vessel density (MVD) scores which reflecting tumor angiogenesis, among the three proteomic groups, and found patients belonged to S-Im showed highest MVDs." (PMID 36720864, 2023). "To validate that PDGFRA and MUC family gene mutations status in G34-DHGs, we reviewed the reports of tumor-sequencing test from 6 external patients, among which WES, a big panel targeting 539 or a small panel targeting 135 tumor genes were respectively performed in every 2 patients." (PMID 35109850, 2022). "The PDGFRA signaling pathway may promote angiogenesis, carcinogenesis, and tumor dissemination." (PMID 36052535, 2022). "Thus, the tumor suppression was resulted from inhibitors and simultaneously targeting PDGFRA and EPHA2 could effectively repress GBM growth in vivo." (PMID 35105853, 2022). "Clinically detected GISTs may be associated with widely different tumour mitotic counts and survival outcomes despite identical KIT mutations, suggesting that the GIST phenotype is influenced by molecular factors other than the primary KIT or PDGFRA mutation." (PMID 35029030, 2022). "Secondary resistance with tumor progression within the first 2 years of treatment remains a significant clinical problem, affecting 40% to 50% of patients under TKI treatment for metastatic GISTs, usually due to resistance mutations occurring in either KIT or PDGFRA." (PMID 34552011, 2021). "However, we did not detect a PDGFRA mutation in our responder or in other tumor samples within the study population." (PMID 34356494, 2021). "ctDNA evaluation might impact particularly in tumor types associated with recurrent driver genetic events, such as GIST, a rare neoplasm of mesenchymal origin whose course of disease is governed by KIT or PDGFRA oncogenic activation." (PMID 32024476, 2020). "Indeed, protein levels of PDGFRα in the patient tumour and TK-RIG915 were concordant." (PMID 33053751, 2020).